PINX1 (PIN2 (TERF1) interacting telomerase inhibitor 1)
Description:
Microtubule-binding protein essential for faithful chromosome segregation. Mediates TRF1 and TERT accumulation in nucleolus and enhances TRF1 binding to telomeres. Inhibits telomerase activity. May inhibit cell proliferation and act as tumor suppressor.
Synonyms: LPTL; LPTS; FLJ20565; MGC8850; Gno1; Pxr1
Tractability: PROTAC: ubiquitination databases record sites on it.
Gene: Protein-coding gene on chromosome 8 (10,764,961 to 10,839,884, reverse strand). Ensembl gene ENSG00000254093.
Subcellular location: Nucleus; Nucleus, nucleolus; Chromosome, telomere; Chromosome, centromere, kinetochore
Subcellular location (Human Protein Atlas): Nucleoli; Mitochondria; Nucleoplasm
Gene Ontology:
Molecular function: protein binding; protein-containing complex binding; telomerase inhibitor activity; telomerase RNA binding; nucleic acid binding
Biological process: mitotic metaphase chromosome alignment; negative regulation of G2/M transition of mitotic cell cycle; negative regulation of protein ubiquitination; negative regulation of telomere maintenance via telomerase; positive regulation of protein localization to nucleolus; protein localization to chromosome, telomeric region; protein localization to nucleolus; regulation of protein stability; telomere maintenance via telomerase; negative regulation of cell population proliferation; negative regulation of telomere maintenance via telomere lengthening
Cellular component: chromosome, telomeric region; kinetochore; nuclear chromosome; nucleolus; nucleoplasm; nucleus; spindle
Genetic constraint (gnomAD): Loss-of-function variants: 15 observed, 10.11 expected, observed/expected ratio (o/e) 1.48, 90% interval 0.97 to 1.92. The synonymous counts are far from expectation, so gnomAD's model fits this gene poorly and the ratio says little. Missense variants: 392 observed, 281.16 expected, observed/expected ratio (o/e) 1.39, 90% interval 1.28 to 1.52. Synonymous variants: 138 observed, 103.94 expected, observed/expected ratio (o/e) 1.33, 90% interval 1.15 to 1.53.
Homologues: Orthologues: chimpanzee PINX1 (98% identical), macaque PINX1 (93% identical), dog PINX1 (76% identical), mouse Pinx1 (73% identical), rat Pinx1 (69% identical), guinea pig PINX1 (68% identical), zebrafish pinx1 (48% identical), Drosophila melanogaster CG11180 (35% identical), Caenorhabditis elegans T23G7.3 (30% identical). Paralogues in human: GPATCH4 (18% identical).
Diseases named in the same sentence as PINX1 in open-access papers:
PINX1 is named in the same sentence as 60 diseases in open-access papers, as found by Europe PMC text mining. Sharing a sentence is not in itself a finding about the gene and the disease. The quoted sentences say what the papers report.
gastric cancer (8 papers, 2013 to 2017). A primary or metastatic malignant neoplasm involving the stomach. "PinX1 downregulation results in poor prognosis in some cancers, including gastric cancer, prostate cancer, ovarian cancer, and breast cancer." (PMID 28815183, 2017). "Reduced expression of PinX1 has been implicated in various human cancers, such as breast cancer, ovarian cancer, gastric cancer and liver cancer, which suggested a tumor suppressor role of pinX1 in multiple human cancers." (PMID 24936151, 2014). "Previous studies have shown that reduced expression of PinX1 is implicated in various human cancers, including breast cancer, ovarian cancer, gastric cancer, and liver cancer, suggesting that PinX1 may function as a tumour suppressor in multiple human cancers." (PMID 28815183, 2017). "LOH of PinX1 resulted in gastric carcinoma development, which suggested PinX1 might have a potential inhibitory role in cancer metastasis." (PMID 25888829, 2015). "Although the relationship between the PinX1 gene and human tumors has been studied widely, such as in medulloblastoma, hepatocelllular carcinoma, prostate cancer, and gastric cancer, the expression and prognostic value of PinX1 protein has not been investigated in UCB." (PMID 24268029, 2013). "Thus, PinX1 can be regarded as a sign of gastric cancer development." (PMID 27556185, 2016).
prostate carcinoma (7 papers, 2012 to 2020). A carcinoma that arises from epithelial cells of the prostate gland. "For example, studies on 159 cases of hereditary prostate cancer identified 39 polymorphisms during PinX1 sequencing; studies on gastrointestinal cancer also found a missense mutation (AGC/TGC) out of 254 codons in 1 case of colon cancer and 1 case of esophageal cancer." (PMID 22316341, 2012). "However, some studies on prostate cancer, gastrointestinal cancer and medulloblastoma indicate that gene polymorphism rather than PinX1 expression is the key factor in inhibiting telomerase and PinX1 as a microtubule binding protein plays an important role in stabilizing chromosome." (PMID 22316341, 2012). "However, the PinX1 expression status and its correlation with the clinicopathological features in prostate cancer (PCa) have not been investigated." (PMID 24936151, 2014).
breast carcinoma (6 papers, 2011 to 2017). "In addition, the potential molecular mechanisms underlying the role of PinX1 in breast cancer are still unclear." (PMID 25888829, 2015). "Our results definitely confirmed that low PinX1 expression is associated with poor prognosis, suggesting that PinX1 may function as a prognostic marker for breast cancer." (PMID 25888829, 2015). "Although decreased expression of PinX1 was observed in breast cancer cell lines, and knockout of PinX1 in mice could cause breast cancer, the role of PinX1 in growth control of breast cancer cells and its molecular mechanism remains unclear." (PMID 24672800, 2014). "Overexpression of PinX1 in breast cancer cell lines caused lower growth rate, G0/G1 phase arrest, and S phase inhibition, whereas knockdown of PinX1 in nontumorigenic breast cell line resulted in higher growth rate, decreased G0/G1 phase, and increased S phase rate." (PMID 24672800, 2014). "The role of PinX1 in breast cancer was demonstrated by Zhou which decreased expression of PinX1 was observed in breast cancer cell lines, and knockout of PinX1 in mice could cause different epithelial cancers including breast cancer." (PMID 24672800, 2014). "However, the association between PinX1 and NF-κB in breast cancer cells exists indeed." (PMID 25888829, 2015). "In our previous study, we demonstrated that PinX1 suppresses renal cell carcinoma and breast cancer invasion and metastasis in vitro and in vivo." (PMID 27556185, 2016). "PinX1 suppressed breast cancer migration and invasion by inhibiting the expression and activity of MMP-9 via NF-κB-dependent transcription." (PMID 25888829, 2015). "Of the 405 breast cancer analyzed, low and high expression of PinX1 staining were 52.3% (212/405) and 47.7% (193/405), respectively." (PMID 25888829, 2015). "We then analyzed the correlations between PinX1 expression and characteristics of the breast carcinomas, and found that PinX1 staining was dramatically decreased in histology grade II and III compared with histology grade I (P = 0.001, χ2 test)." (PMID 25888829, 2015). "Consistently, the increased ability of migration and invasion induced by PinX1 knockdown was also suppressed by inhibition of NF-κB-p65 expression in breast cancer cells." (PMID 25888829, 2015). "So we supposed PinX1 suppress migration and invasion of breast cancer cells by regulating MMP-9 expression and activity." (PMID 25888829, 2015). "To investigate the mechanisms of PinX1 regulating migration and invasion in breast cancer cells, we performed western blot to detect the MMPs protein levels and gelatin zymography to observe the MMPs activity." (PMID 25888829, 2015). "Our data demonstrated that PinX1 inhibited breast cancer cells’ migration and invasion abilities by down-regulating MMP-9 expression and activity in vitro." (PMID 25888829, 2015). "In the present study, we used a breast cancer TMA containing 405 tumor samples with specific clinical data to investigate the role of PinX1 in human breast cancer." (PMID 25888829, 2015). "Lastly, we set up the nude mice model by Tail vein assay to exam the functional role of PinX1 in breast cancer metastasis." (PMID 25888829, 2015). "We investigated that PinX1 overexpression in breast cancer cells significantly inhibited the formation of metastasis nodules in lung of nude mice." (PMID 25888829, 2015). "Our results confirmed the role of PinX1 as a major tumor suppressor gene in breast cancer cell lines and provided information for further research on the molecular mechanisms of PinX1 in tumorigenesis." (PMID 24672800, 2014). "We show that PinX1 is reduced in most human breast cancer tissues and cells and that reducing PinX1 levels leads to telomerase activation, telomere elongation and chromosome instability." (PMID 22021332, 2011). "PinX1 is downregulated in a large subset of human breast cancer tissues and in most breast cancer cell lines examined." (PMID 22021332, 2011).
breast carcinoma (continued). "Moreover, PinX1 protein expressions are reduced in human breast cancer tissues and most breast carcinoma cell lines." (PMID 27556185, 2016). "Furthermore, we demonstrated that PinX1 suppressed breast cancer migration and invasion by inhibiting the expression and activity of MMP-9 via NF-κB-dependent transcription in vitro and in vivo." (PMID 25888829, 2015). "The univariate Cox regression analyses revealed that PinX1 expression was an independent prognostic marker for breast cancer patients overall survival (hazard ratio, 0.573; 95% CI, 0.371-0.884; P = 0.012) and disease-specific survival (hazard ratio, 0.417; 95% CI, 0.230-0.755; P = 0.004)." (PMID 25888829, 2015). "In conclusion, loss of PinX1 expression was significantly correlated with breast cancer progression and was an independent negative prognostic factor in breast cancer patients." (PMID 25888829, 2015). "Moreover, we identified that PinX1 inhibited the migration and invasion of breast cancer by suppressing MMP-9 expression and activity via NF-κB-dependent transcription in vitro." (PMID 25888829, 2015). "To further confirm whether PinX1 regulated MMP-9 expression via the NF-κB signaling pathway in human breast cancer cells, we transfected NF-κB-p65 siRNA (Santa Cruz) into PinX1KD-MDA-MB-231 cells and PinX1KD-BT-549 cells." (PMID 25888829, 2015). "We investigated the involvement of PinX1 in breast cancer cells migration and invasion." (PMID 25888829, 2015). "This study was designed to evaluate the role of PinX1 in human breast cancer." (PMID 25888829, 2015). "Our study suggested the role of PinX1 as a major tumor suppressor gene in breast cancer cell lines." (PMID 24672800, 2014). "As a major tumor suppressor gene, the role of PinX1 in breast cancer and its molecular mechanism remain unclear." (PMID 24672800, 2014). "The results showed a lower growth rate in the pcDNA3.1-PinX1 transfected MCF-7 breast cancer cell line than the untransfected and vector transfected control cells and a higher growth rate in the PinX1 knockdown MCF-10A cell line than the untransfected and siRNA NC transfected control cells." (PMID 24672800, 2014). "In our study, we also found that the overexpression of PinX1 could alter the lncRNA expression profile in MCF-7 breast cancer cells." (PMID 24672800, 2014). "Finally, our mice model confirmed that PinX1 suppressed breast cancer metastasis in vivo." (PMID 25888829, 2015). "Moreover, we examined whether PinX1 expression was an independent prognostic factor for breast cancer." (PMID 25888829, 2015). "Lastly, we examined whether PinX1 suppressed breast cancer metastasis in vivo." (PMID 25888829, 2015). "However, the role of PinX1 in growth control of breast cancer cells and its molecular mechanism remains unclear." (PMID 24672800, 2014). "Furthermore, PinX1 is reduced in a large subset of human breast cancer tissues and cells." (PMID 22021332, 2011). "Therefore PinX1 may be an attractive therapeutic target for the treatment of breast cancer." (PMID 25888829, 2015). "To evaluate the function of PinX1 in breast cancer, we used a tissue microarray (TMA) of human breast cancer patients and immunohistochemistry to analyze the correlation between PinX1 expression and clinicopathologic variables and patient survival." (PMID 25888829, 2015). "To evaluate the function of PinX1 in breast cancer, we used a tissue microarray (TMA) of 405 human breast cancer patients and immunohistochemistry to analyze the correlation between PinX1 expression and clinicopathologic variables and patient survival." (PMID 25888829, 2015). "Recent years, our research team validated that low PinX1 expression was an independent negative prognostic factor for clear cell renal cell carcinoma (ccRCC), breast cancer (BC) and gliomas patients." (PMID 27556185, 2016). "Cox regression analysis revealed that low PinX1 expression was an independent negative prognostic indicator for breast cancer patients." (PMID 25888829, 2015).
breast carcinoma (continued). "Our data revealed that low PinX1 expression was an independent negative prognostic factor for breast cancer patients." (PMID 25888829, 2015). "In this study, overexpression of PinX1 was generated in 3 breast cancer cell lines, and knockdown of PinX1 was performed in a nontumorigenic breast cell line." (PMID 24672800, 2014). "The qRT-PCR and western blotting results indicated that pcDNA3.1-PinX1 transfected breast cancer cell lines MCF-7, MDA-MB-231 and SK-BR-3 showed a higher PinX1 expression level than their counterpart untransfected cells and empty vector transfected control cells." (PMID 24672800, 2014). "We found a lower growth rate, G0/G1 phase arrest, and S phase inhibition in the PinX1 overexpressed breast cancer cells, while a higher growth rate, decreased G0/G1 phase, and increased S phase rate in the PinX1 knocked-down nontumorigenic breast cell." (PMID 24672800, 2014). "However, the PinX1 expression status and its correlation with the clinicopathological features in breast cancer have never been investigated." (PMID 25888829, 2015). "However, the expression and function of PinX1 in breast cancer and its correlation with the clinicopathological features of breast cancer patients have never been investigated." (PMID 25888829, 2015). "However, overexpression or knockdown of PinX1 had no detectable effect on the proliferation of breast cancer cells under normal culture conditions (data not shown)." (PMID 25888829, 2015). "Therefore, in this study, we generated MCF-7, MDA-MB-231, and SK-BR-3 breast cancer cells stably overexpressing PinX1 and MCF-10A nontumorigenic breast cell knocking down PinX1 and assessed the role of PinX1 in growth control of the cells by MTT assay, focus formation, and flow cytometry." (PMID 24672800, 2014).
ovarian carcinoma (6 papers, 2014 to 2024). A malignant neoplasm originating from the surface ovarian epithelium. "Our finding provided epidemiologic evidence that PINX1 genetic variants could affect ovarian cancer outcome through telomere maintenance pathway." (PMID 28233473, 2017). "To further assess the impact of PINX1 deficiency on the efficacy of PARP inhibitors in vivo, we established a xenograft model in NSG mice using ovarian carcinoma-derived cell line OC316 with or without PINX1 knock-down." (PMID 39174499, 2024).
colorectal cancer (5 papers, 2017 to 2025). A primary or metastatic malignant neoplasm that affects the colon or rectum. "The results of the subgroup analysis showed that low PINX1 expression was associated with significantly poorer OS in colorectal cancer, non-small cell lung cancer, sample size (> 150), and test method (IHC + TMA)." (PMID 30079348, 2018). "In a subgroup analysis of tumor type, low PINX1 expression was associated with significantly poorer OS for colorectal cancer (HR: 2.28, 95.0% CI: 1.46–3.56; P < 0.001) and non-small cell lung cancer (HR: 1.48, 95.0% CI: 1.06–2.08; P = 0.023)." (PMID 30079348, 2018). "In this study, we revealed that PinX1 is highly expressed in colorectal cancers (CRC) and promotes tumor cell proliferation." (PMID 40639785, 2025). "Therefore, PINX1 expression is a potential biomarker of prognostic significance for OS and DFS/RFS in colorectal cancer and non-small cell lung cancer." (PMID 30079348, 2018). "Both the 5-year OS and 5-year DFS in patients with colorectal cancer are lower in patients with low/negative expression of PinX1 protein compared with that in patients with high/moderate expression of PinX1 which is consistent with our current findings." (PMID 28815183, 2017).
lung carcinoma (5 papers, 2016 to 2022). "Moreover, we use pinX1 siRNA to investigate the underlying mechanisms, and a similar experiment in vivo based on pinX1 transgenic mice will provide more clues for the study of the mechanism of hesperidin against lung cancer." (PMID 35847001, 2022). "In order to investigate the role of pinX1 in lung cancer, the pinX1 expression was knocked down by its specific siRNA in vitro." (PMID 35847001, 2022). "In HPA, we found that the expression of pinX1 was poor in normal lung tissues, whereas the staining intensity was moderate or strong in lung cancer." (PMID 35847001, 2022). "In this study, we found that the pinX1 expression level is closely related to overall survival and plays an important role in regulating lung cancer cell proliferation, migration, invasion, and senescence." (PMID 35847001, 2022). "In order to explore the role of pinX1 in exact lung cancer, the role of pinX1 was investigated using a shared database." (PMID 35847001, 2022). "The PinX1 protein was highly expressed in 46 of the 86 (53.49%) lung cancer tissues, while the low expression of pinX1 was observed in 77 of the 86 (89.53%) adjacent samples." (PMID 35847001, 2022). "It is also indeed important to detect the pinX1 expression profile in other lung cancer cell lines and to verify the broad applicability of the anti-lung cancer effect of hesperidin." (PMID 35847001, 2022). "LncRNA CCAT2 can promote the proliferation of lung cancer cells by affecting Wnt signaling pathway, lncRNA PinX1 can block the growth of lung cancer cells in G0/G1 phase, thus inhibiting the proliferation of lung cancer and acting as anti-tumor effect." (PMID 33976738, 2021). "Since PinX1 is an inner telomerase inhibitor, we first detected the effects of PinX1 on telomerase activity in lung cancer cells." (PMID 28815183, 2017). "In this study, we found that hesperidin inhibits lung cancer in vitro and in vivo via pinX1." (PMID 35847001, 2022). "Interestingly, the pinX1 protein expression in lung cancer patients is positively related to overall survival time, which is in accordance with a study on thyroid cancer." (PMID 35847001, 2022). "Differential expression of pinX1 in lung cancer and adjacent tissues." (PMID 35847001, 2022). "According to our mutation data, PinX1 mutations in gastric, colorectal, prostate, breast, and lung carcinomas may not actually contribute to development of these carcinomas due to their low incidence of mutational events seen in the database." (PMID 28978030, 2017).